FGFR2 (fibroblast growth factor receptor 2)
Diseases named in the same sentence as FGFR2 in open-access papers (continued):
Sharing a sentence is not in itself a finding about the gene and the disease.
cholangiocarcinoma (continued). "For instance, fibroblast growth factor receptor 2 (FGFR2) rearrangements in cholangiocarcinoma predict tumor sensitivity to FGFR2 inhibitors." (PMID 38357305, 2024). "Of the four members (FGFR 1–4), FGFR2 aberrations have been identified as the oncogenic drivers of the pathogenesis of cholangiocarcinoma." (PMID 38339363, 2024). "This study evaluated the antitumor activity and safety of pemigatinib in previously treated Chinese patients with advanced cholangiocarcinoma and fibroblast growth factor receptor 2 (FGFR2) fusions or rearrangements." (PMID 36127767, 2023). "A phase II (NCT02265341) is registered to determine the efficacy of ponatinib, a type IIA multi-target tyrosine kinase inhibitor, in patients with advanced cholangiocarcinomas harboring FGFR2 fusions." (PMID 37681152, 2023). "Targetable fibroblast growth factor receptor 2 (FGFR2) and Kirsten rat sarcoma virus (KRAS) mutations were detected in 5% of ctDNA samples from patients with cholangiocarcinoma." (PMID 37108676, 2023). "Mutations in FGFR2 have been detected in 5.6% and FGFR2 and KRAS mutations in 5% in the present study of ctDNA samples from cholangiocarcinoma patients, with other targetable aberrations identified in <6% to 44% of cholangiocarcinoma patients." (PMID 37108676, 2023). "Several FGFR inhibitors demonstrated activity in cholangiocarcinoma and urothelial cancer harboring FGFR2 and FGFR3 alterations." (PMID 37681152, 2023). "Bridging this gap, we report results of the first round robin test for FGFR2 fusions in cholangiocarcinoma and contextualise test data with genomic architecture." (PMID 36635225, 2023). "Of note, EGFR bypass activation has been reported as an early event in the setting of FGFR inhibition in FGFR3-altered urothelial cancer and in FGFR2-driven cholangiocarcinoma, suggesting the potential of EGFR targeting in progressive FGFR-driven diseases." (PMID 37377403, 2023). "It is the first targeted treatment approved for cholangiocarcinoma in the United States, the European Union, Japan, and Taiwan (China), indicated for previously treated cholangiocarcinoma with an FGFR2 fusion or rearrangement." (PMID 36127767, 2023). "•Pemigatinib, infigratinib, and futibatinib are approved for cholangiocarcinoma positive for FGFR2 fusions or rearrangements." (PMID 37681152, 2023). "FGFR2 GAs, which are mostly fusions, are found in 10-15% of intrahepatic cholangiocarcinoma’s, compared to 4.4% in our KRAS wild-type PDA cohort." (PMID 37404765, 2023). "In this study, we report the results of a multi‐centre round robin test of FGFR2 fusion testing in cholangiocarcinoma by targeted NGS‐based RNA analysis and FISH." (PMID 36635225, 2023). "Of note, the characteristics of the FGFR3 kinase domain at resistance are distinctly different from what has been observed in FGFR2-driven cholangiocarcinoma." (PMID 37377403, 2023). "Patients with cholangiocarcinoma carrying FGFR2 fusions or rearrangements represent a distinct genetic subgroup, associated with specific histopathological phenotypes and prognoses." (PMID 36127767, 2023). "Futibatinib has proven to be a valuable treatment for patients with FGFR2 abnormalities with cholangiocarcinoma." (PMID 37048074, 2023). "This is the first study providing evidence for the efficacy and safety of pemigatinib among Chinese patients with cholangiocarcinoma carrying FGFR2 fusions or rearrangements." (PMID 36127767, 2023). "After that, Infigratinib was granted accelerated approval by FDA for cholangiocarcinoma with an FGFR2 fusion or rearrangement." (PMID 37370984, 2023). "A phase I/II study (NCT01752920), including patients (n = 29) with cholangiocarcinoma with FGFR2 fusions, demonstrated an ORR of 20.7%, DCR of 82.8%, and a mPFS of 5.7 months (95% CI, 4.0–9.2)." (PMID 37681152, 2023). "Pemigatinib is the first targeted therapeutic agent approved in the United States for cholangiocarcinoma with FGFR2 fusions or rearrangements." (PMID 37370984, 2023).
cholangiocarcinoma (continued). "The FGFR-tyrosine kinase inhibitor (TKI) pemigatinib has been introduced in the treatment of advanced cholangiocarcinoma and more recently for relapsed or refractory myeloid/lymphoid neoplasms with FGFR2 and FGFR1 rearrangements, respectively." (PMID 37715207, 2023). "Pemigatinib (FIGHT-302) and futibatinib (FOENIX-CAA3) are being evaluated in phase III trials that compare these agents to current first-line gemcitabine and cisplatin in FGFR2-rearranged cholangiocarcinoma." (PMID 37681152, 2023). "We also report results from a molecular epidemiology study of FGFR2 rearrangements in Chinese patients with cholangiocarcinoma." (PMID 36127767, 2023). "Better results were observed in patients affected by cholangiocarcinoma patients with FGFR2 alterations, for which the drug received accelerated approval." (PMID 38067258, 2023). "SOX9, which is stimulated by the Wnt/β‐catenin pathway, enhances the transcription and expression of FGF7 and FGFR2, thereby stimulating the downstream pathway of FGFR2 to promote the proliferation of cholangiocarcinoma cells and resistance to pemigatinib." (PMID 37750089, 2023). "A study (NCT04507503) is providing expanded access to futibatinib for patients diagnosed with advanced cholangiocarcinoma exhibiting FGFR2 rearrangements." (PMID 37681152, 2023). "•Superior responses to FGFR inhibitors are observed in cholangiocarcinomas exhibiting FGFR2 fusions and rearrangements." (PMID 37681152, 2023). "No new safety signals were reported, and promising efficacy was observed with responses across tumor types including cholangiocarcinoma with FGFR2 alterations." (PMID 37000035, 2023). "Clinical responses were observed with five PRs across different tumor types including cholangiocarcinoma with FGFR2 alterations." (PMID 37000035, 2023). "The encouraging antitumor activity and favorable safety profile support the use of pemigatinib as a treatment in previously treated Chinese patients with cholangiocarcinoma and FGFR2 rearrangements." (PMID 36127767, 2023). "It has received FDA accelerated approval for the treatment of FGFR2-rearranged cholangiocarcinoma with FGFR2 rearrangements." (PMID 38067258, 2023). "Most recently, the next-generation FGFR1-4 inhibitor futibatinib has also shown activity and a tolerable safety profile in the treatment of advanced cholangiocarcinoma with FGFR-2 fusions or rearrangements." (PMID 38203714, 2023). "Collectively, these data indicate that testing for FGFR2 gene fusions is becoming a critical standard of care in patients with cholangiocarcinoma." (PMID 36635225, 2023). "Through activation of the AKT/mTOR pathway, FGFR2 reduces the sensitivity of cholangiocarcinoma to gemcitabine." (PMID 37750089, 2023). "Pemigatinib is the first United Stated Food and Drug Administration (FDA)-approved FGFR inhibitor for FGFR2 fusion in cholangiocarcinoma." (PMID 37681152, 2023). "The US FDA has also granted approval to pemigatinib for the management of advanced cholangiocarcinoma patients characterized by fibroblast growth factor receptor 2 (FGFR2) translocations." (PMID 37964396, 2023). "In one study, tumor volume reduction was observed in a patient with cholangiocarcinoma harboring FGFR2 fusions in response to BGJ398." (PMID 37681152, 2023). "Xenograft models of cholangiocarcinoma with infigratinib have shown that it activates FGFR2 and FGFR3 alterations." (PMID 37954763, 2023). "Eight patients with a diagnosis of colorectal, pancreatic, esophageal, breast, thyroid, gastric, or cholangiocarcinoma had an FGFR2 alteration and received erdafitinib or derazantinib." (PMID 37175010, 2023). "Pemigatinib provided clinical benefits for previously treated patients with cholangiocarcinoma carrying FGFR2 fusions or rearrangements and was approved for this indication in multiple countries." (PMID 36127767, 2023).
cholangiocarcinoma (continued). "One of the most prevalent genome rearrangements that gives rise to cholangiocarcinomas is a fusion between the genes encoding FGFR2 (Fibroblast growth factor receptor 2) and BICC1 that results in the production of an FGFR2-Bicc1 fusion protein." (PMID 36158189, 2022). "FGFR2 gene fusions are most frequent in cholangiocarcinoma, and are also detected, albeit less commonly, in colorectal cancer, hepatocarcinoma and NSCLC." (PMID 35402233, 2022). "Pemigatinib, the first FGFR1/2/3 selective inhibitor received accelerated FDA approval for patients carrying FGFR2 fusion/rearrangement in cholangiocarcinoma." (PMID 36147913, 2022). "Infigratinib was approved by FDA for the treatment of cholangiocarcinoma patients with FGFR2 fusion in 2021." (PMID 35494629, 2022). "Treatment options, which improve clinical outcomes of patients with cholangiocarcinoma (CCA) harboring FGFR2 gene fusions, have been extended to the first two targeted therapies, i.e., pemigatinib and infigratinib." (PMID 35408658, 2022). "EWSR1 gene fusion was found in 6 cases of sarcoma, and FGFR2 fusion in 1 case of cholangiocarcinoma and 1 case of salivary duct carcinoma." (PMID 36088851, 2022). "Patients with cholangiocarcinoma and disease progression after at least one previous treatment were assigned to one of three cohorts: patients with FGFR2-fusions or rearrangements, patients with other FGFR alterations, or patients with no FGFR alterations." (PMID 35444941, 2022). "Futibatinib is the most advanced candidate in the category of covalent pan-FGFR inhibitors because it is in phase 3 clinical trial to evaluate the treatment of metastatic and recurrent unresectable cholangiocarcinoma harboring FGFR2 gene rearrangements." (PMID 35494629, 2022). "On April 2020, the U.S. Food and Drug Administration (FDA) approved pemigatinib for the treatment of patients with previously treated advanced cholangiocarcinoma with FGFR2-fusion or rearrangement." (PMID 35444941, 2022). "It shows manageable toxicity and meaningful clinical activity against chemotherapy-refractory cholangiocarcinoma FGFR2 fusions/rearrangements." (PMID 36209184, 2022). "In the dose expansion phase, of the 18 patients enrolled for evaluable response, 5 had cholangiocarcinoma, of which 4 harbored FGFR2-fusion and one with FGFR1-fusion, being the only one who had PD after treatment." (PMID 35444941, 2022). "For example, pemigatinib, a FGFR-specific tyrosine kinase inhibitor, has been approved by the US Food and Drug Administration (FDA) for advanced cholangiocarcinoma with FGFR2 fusions or rearrangements." (PMID 35039066, 2022). "Pemigatinib exhibits a manageable safety profile and durable antitumor activity in previously treated patients with cholangiocarcinoma harboring FGFR2 fusions/rearrangements." (PMID 36209184, 2022). "The approval of pemigatinib and infigratinib were based on phase II studies where a median PFS of approximately 7 months was reached in patients with chemo-refractory cholangiocarcinoma with FGFR2 gene fusions." (PMID 36290832, 2022). "One oesophageal cancer case harboured an FGFR2 fusion, predicting sensitivity to erdafitinib and pemigatinib, which are approved in cholangiocarcinoma and bladder cancers." (PMID 35849877, 2022). "Our data indicate that an appropriate NGS approach is recommended to reliably identify FGFR2 gene fusion in cholangiocarcinoma." (PMID 35871236, 2022). "It has been reported that FGFR2 fusions occur with diverse fusion partners, especially in cholangiocarcinoma, and these genetic aberrations of FGFR2 induce cancer cell proliferation and tumorigenesis." (PMID 35342406, 2022). "FGFR2-fusions are an important target in cholangiocarcinoma to date; however, after an initially higher RR to these agents, most tumors will develop disease progression." (PMID 35444941, 2022).
cholangiocarcinoma (continued). "Pemigatinib is a potent inhibitor of the fibroblast growth factor receptor (FGFR) family of receptors that is approved for the treatment of cholangiocarcinoma with FGFR2 fusion or other rearrangements." (PMID 34951522, 2022). "Fibroblast growth factor receptor 2 (FGFR2) fusion proteins were reported to promote oncogenic transformation of mouse liver organoids to cholangiocarcinoma." (PMID 35551634, 2022). "It is promising that there has been recent developments and approval of targeted therapies for cholangiocarcinomas with FGFR2 fusions and for solid tumors with NTRK fusions." (PMID 36333410, 2022). "A retrospective analysis of 17 cholangiocarcinoma cases revealed FGFR2-3 alterations in 82.3% of archival tumour samples and 50% of DNA samples (4/5 SNVs, 1/2 amplifications, and 5/13 fusions)." (PMID 35402233, 2022). "In the majority of cases, genomic alterations mainly comprised SVs, except for FGFR1 alterations in salivary gland carcinoma and FGFR2 alterations in cholangiocarcinoma, in which REs were most common." (PMID 36462464, 2022). "A phase 3 FIGHT-302 clinical trial of first-line pemigatinib vs. gemcitabine plus cisplatin for advanced cholangiocarcinoma harboring FGFR2 fusions/rearrangements is still ongoing." (PMID 36209184, 2022). "Pemigatinib and infigratinib are FGFR1‐3 inhibitors approved for previously treated cholangiocarcinoma with an FGFR2 fusion or other rearrangements." (PMID 36254250, 2022). "In cholangiocarcinoma, of which intrahepatic was the most common type, FGFR2 alterations were the most frequent genomic alteration, with REs comprising the majority." (PMID 36462464, 2022). "Pemigatinib, a selective FGFR inhibitor, showed a 35% response rate in patients with FGFR2 fusion-positive advanced cholangiocarcinoma in a prospective phase II trial." (PMID 36661679, 2022). "Fibroblast growth factor receptors (FGFR) are a family of transmembrane proteins with tyrosine kinase domains, which are commonly mutated or fused in urothelial, breast, and gynecologic cancers, as well as cholangiocarcinomas (commonly FGFR2)." (PMID 34439216, 2021). "The safety and efficacy of Futibatinib are now being compared with standard of care (gemcitabine-cisplatin) in a multicenter phase 3 study of patients with advanced cholangiocarcinoma with FGFR2 gene rearrangements (NCT04093362)." (PMID 34680318, 2021). "The FDA recently approved an FGFR2 inhibitor, pemigatinib, which demonstrated a survival benefit in patients with cholangiocarcinoma with FGFR2 rearrangement or alteration." (PMID 34440089, 2021). "Results from phase II trials of Infigratinib (BGJ398), a FGFR2 kinase inhibitor, exhibited manageable toxicity and significant clinical effect on chemotherapy-refractory cholangiocarcinoma containing FGFR2 fusions." (PMID 33692336, 2021). "On the basis of positive results, the US FDA has approved the anti‐FGFR2 antibody pemigatinib in 10‐16% of patients with cholangiocarcinoma harbouring FGFR2 gene fusions." (PMID 33277810, 2021). "Several pre-clinical studies and clinical trials have demonstrated that FGFR2 rearrangements in cholangiocarcinoma can predict tumor sensitivity to FGFR2 inhibitors and become an important therapy in these highly selected patients." (PMID 34551773, 2021). "For instance, the FGFR2/3 fusion seen in approximately 40% of cholangiocarcinoma is a target for the drug pemagatinib." (PMID 33632293, 2021). "In cholangiocarcinoma, FGFR2 mutations are as high as 20%, and up to 13% of ICCs have fibroblast growth factor receptor 2 (FGFR2) fusion genes." (PMID 34367944, 2021). "Another selective FGFR inhibitor, pemigatinib, was also recently granted accelerated approval for treatment of late stage FGFR2+ cholangiocarcinoma patients." (PMID 33710807, 2021). "A previous study reported that FGFR2 fusions are observed mostly in cholangiocarcinoma, occurring in 10–16% of patients." (PMID 33968743, 2021).
cholangiocarcinoma (continued). "Noteworthy, both fused and unfused amplified FGFR2 products are targetable molecular alterations, and current clinical protocols in gastric cancer and cholangiocarcinoma address with some success both forms." (PMID 33853673, 2021). "In our study, we found that cholangiocarcinoma had the highest frequency of FGFR2 alteration, and fusion accounted for the major proportion." (PMID 33968743, 2021). "In a clinical study of three patients with FGFR2-fusion cholangiocarcinoma receiving BGJ398 therapy, all patients developed acquired resistance with FGFR2 gatekeeper V564F mutation." (PMID 33568192, 2021). "FGFR2 fusions have been considered a promising therapeutic target for cholangiocarcinoma in clinical practice after the FDA-accelerated approval of pemigatinib to treat cholangiocarcinoma patients carrying FGFR2 fusions or rearrangements." (PMID 34732230, 2021). "These encouraging data demonstrate the potential benefit of pemigatinib in cholangiocarcinoma patients with FGFR2 fusions or rearrangements." (PMID 34732230, 2021). "The efficacy of pemigatinib was evaluated in a phase II study (NCT02924376) among 107 cholangiocarcinoma patients harboring chimeric FGFR2 proteins." (PMID 34732230, 2021). "With the accelerated approval of erdafitinib for FGFR‐altered urothelial carcinoma in April 2019 and pemigatinib for cholangiocarcinoma with FGFR2 fusion or other rearrangements in April 2020,6, 7 the FGF‐FGFR signalling pathway has received more attention." (PMID 33655556, 2021). "Particularly, the European Medicines Agency (EMA) approved in April 2021 the use of Pemigatinib for previously treated advanced cholangiocarcinomas showing FGFR2 fusion or rearrangement." (PMID 34768421, 2021). "A cholangiocarcinoma patient was described with a fusion comprising FGFR2 and NDC80 (or HEC1, highly expressed in cancer 1)." (PMID 34207779, 2021). "Two phase I clinical trials which have been published demonstrated the safety and efficacy of derazantinib in FGFR2 fusion‐positive intrahepatic cholangiocarcinoma and urothelial cancer with FGFR2 and FGF19 amplification." (PMID 33655556, 2021). "Compared to the high frequency of FGFR2 fusions in cholangiocarcinoma, FGFR3 fusions are more commonly detected in urothelial carcinoma and glioblastoma multiforme (GBM), with fewer cases detected in lung cancer." (PMID 34732230, 2021). "The irreversible FGFR inhibitor futibatinib is currently under evaluation in a phase III clinical study in patients with advanced cholangiocarcinoma harboring FGFR2 gene rearrangements (ClinicalTrials.gov Identifier: NCT04093362)." (PMID 32962091, 2020). "FGFR2 activation by point mutations and FGFR1–3 amplification or overexpression are also observed in subsets of patients with advanced cholangiocarcinoma." (PMID 32325878, 2020). "In this technical report, we describe the generation of an endogenous FGFR2–Bicaudal family RNA binding protein 1 (BICC1) fusion in multiple independent cholangiocarcinoma and immortalized liver cell lines using CRISPR." (PMID 32252259, 2020). "This profile translates into potentactivity in xenograft tumor models with translocations in FGFR1 (8p11-translocatedmyeloid leukemia), FGFR2 (cholangiocarcinoma), and FGFR3 (urothelial carcinoma)." (PMID 32315352, 2020). "Pemigatinib was granted FDA-accelerated approval in April 2020 for the treatment of cholangiocarcinoma patients with FGFR2 fusions or rearrangements." (PMID 32962091, 2020). "The efficacy of the drug was evaluated in the FIGHT-202 study in 107 patients with cholangiocarcinoma and FGFR2 gene fusions." (PMID 32962091, 2020). "Genomic alterations, mostly rearrangements, in FGFR2 are commonly reported in cholangiocarcinoma patients in Western countries, and these alterations result in constitutive activation of the FGFR2 receptor." (PMID 32631434, 2020). "Anchored multiplex PCR has been recently used to identify various FGFR2 fusions in cholangiocarcinoma clinical samples." (PMID 32962091, 2020).